ELF3 (E74 like ETS transcription factor 3)
Diseases named in the same sentence as ELF3 in open-access papers (continued):
Sharing a sentence is not in itself a finding about the gene and the disease.
gastric cancer (12 papers, 2019 to 2025). A primary or metastatic malignant neoplasm involving the stomach. "ELF3 is one of the ETS family transcription factors that was expressed in gastric cancers at higher levels than in normal epithelium and was mutated in a small minority of gastric cancers, representing one of the most prevalently mutated factors of the family." (PMID 41425714, 2025). "Despite being over-expressed in a sub-set of gastric cancers, ELF3 has functions that are generally associated with tumor suppression such as repressing epithelial-mesenchymal transition (EMT) and promoting the reverse process, mesenchymal to epithelial transition (MET)." (PMID 41425714, 2025). "In gastric cancer, a role of the up-regulation of family member ELF3 has been suggested as part of the network of transcription factors up-regulated by triggers inducing intestinal metaplasia." (PMID 41425714, 2025). "The group without ELF3/HNF4A up-regulation also had a higher percentage of early onset (diagnosis at age less than 50 years old) gastric cancers (21.4% vs. 4.3% in the group with ELF3/HNF4A up-regulation." (PMID 41425714, 2025). "This aligns with emerging evidence that elf3 directly binds to the IRF6 promoter in a human gastric cancer cell line and to the interferon epsilon promoter in HEK293 cells." (PMID 41147741, 2025). "mRNA expression levels of ETS family members in gastric carcinoma tissues were variable, with ELF3, ETS2, EHF, ERF, and ELF1 being the family members with the highest expression." (PMID 41425714, 2025). "The level of mRNA expression of ETS family members in gastric carcinoma tissues was also variable with ELF3, ETS2, EHF, ERF and ELF1 being the family members with the highest expression." (PMID 41425714, 2025). "Conversely, in five of these genes, all clonally mutated patients had mutations that were likely pathogenic (CTNNB1, ELF3, ATM, KMT2E, and PIK3CA), lending stronger support to their candidate gastric cancer driver status." (PMID 36970058, 2022). "In gastric cancer, ELF3 maintains epithelial-like phenotype, prevents EMT and is associated with longer survival, acting as a putative tumor suppressor." (PMID 33618713, 2021). "Here, we chose SGC7901 and AGS gastric cancer cell lines to perform the RNA interference experiment and ELF3 overexpression experiment." (PMID 31019894, 2019). "The family member ELF3 was well expressed in the mRNA level in a subset of gastric cancers (n = 91), and its expression correlated with the expression of other transcription factors involved in gastric cancer pathogenesis, including HNF4A, HNF1A, CDX2, GATA4, GATA6, and EHF." (PMID 41425714, 2025). "ELF3 is a prominent member with relevance in gastric cancer, and its up-regulation, observed in sub-sets of the disease, defines cancers with specific characteristics that may provide targeted therapeutic opportunities." (PMID 41425714, 2025). "Amplifications of ERBB2 and CCND3 were significantly more frequent in ELF3/HNF4A up-regulated gastric cancers (28.6% and 20.4%, respectively) compared with the group of non-up-regulated cancers (2.4% and none, Student’s t-test p = 0.0006 and 0.001, respectively)." (PMID 41425714, 2025). "It was identified that ELF3 was co-expressed with IRF6 in all five gastric cancer GSE datasets." (PMID 31019894, 2019). "ELF3, together with KLF5 and EHF overexpression, has been shown to characterize a subset of peritoneal metastatic gastric cancers through the induction of super-enhancers." (PMID 41425714, 2025).
gastric cancer (continued). "The expression of two other transcription factors, ELF3 and KLF5, also correlated with the expression of CDX2 in gastric cancer (Spearman correlation coefficient 0.21, p = 1.07 × 10−5, and Spearman correlation coefficient 5.49, p = 1.07 × 10−13, respectively)." (PMID 39768557, 2024). "Further, in gastric cancer, an antagonistic relation between ZEB1 and ELF3 was observed through their downstream targets, such as IRF6." (PMID 36864480, 2023). "FZD5, ELF3, TEAD1 and SNAI2 expression in 55 gastric cancer tissues was detected by immunohistochemistry." (PMID 33618713, 2021). "Considering highly similar expression profile between ELF3 and IRF6 in normal human stomach tissues, we wanted to know if ELF3 and IRF6 were still co-expressed in the gastric cancer tissues." (PMID 31019894, 2019). "High co-expression of ELF3 and HNF4A is shown in the current study to lead predominantly to gastric cancers with intestinal histology, lower grade, commonly earlier stage, and the CIN phenotype compared with cancers without up-regulated ELF3/HNF4A co-expression." (PMID 41425714, 2025). "Next, a comparison of the sub-set of gastric cancer patients with up-regulated expression of ELF3 and HNF4A with patients who displayed no ELF3 and HNF4A mRNA up-regulation was performed." (PMID 41425714, 2025). "The absence of ELF3/HNF4A up-regulation seems to define a subgroup of gastric cancers with high rates of genomic stability and diffuse histology." (PMID 41425714, 2025). "Detailed dissection of the role of ELF3 and HNF4A in gastric cancer could be performed in studies using CRISPR or siRNA models." (PMID 41425714, 2025). "ETS family members with the highest protein level of expression in many gastric cancer samples include ETV5, ETV4 and ETV3, while ELF2 and ELF3 had moderate to high levels of expression in all samples tested in the Human Protein Atlas but only in one of the two antibodies checked for each protein." (PMID 41425714, 2025). "The high level of CIN in gastric cancers with up-regulation of ELF3 and HNF4A is a feature not currently clinically targetable, but efforts to develop drugs are ongoing." (PMID 41425714, 2025). "The overall survival (OS) of the two groups of gastric cancers with and without ELF3 and HNF4A concomitant up-regulation was not different (Log Rank test p = 0.24)." (PMID 41425714, 2025). "Interrogation of CCLE database revealed that FZD5 is positively correlated with epithelial-related factors CDH1 (E-cadherin), OCLN (Occludin), EPCAM and ELF3, while negatively correlated with mesenchymal-related factors VIM (Vimentin), SNAI2 (Slug), ZEB1 and ZEB2 in 37 gastric cancer cell lines." (PMID 33618713, 2021). "KLF5 is also frequently amplified in gastric cancer and has recently been shown to regulate gene expression in OAC in combination with other transcription factors, GATA6, ELF3 and EHF." (PMID 32880368, 2020). "Expression of E74 like ETS transcription factor 3 (ELF3), an ETS transcription family member, correlates with expression of other key factors in gastric cancer and confers specific characteristics that may become exploited in targeted therapeutic interventions." (PMID 41425714, 2025).
bladder cancer (11 papers, 2015 to 2025). "Since the L329P mutation in ELF3 is deposited in the TCGA dataset for bladder cancer, the corresponding L285P mutation in EHF was further investigated." (PMID 33712555, 2021). "Similar to bladder cancer, inactivating and splice site mutations in ELF3 occur in ~6% of mucinous OCs." (PMID 30200227, 2018). "Comparatively, categorization of bladder cancers into luminal or basal subtypes identified more frequent ELF3 mutations in luminal tumours." (PMID 30200227, 2018). "A recent exome-sequencing study of bladder cancer performed by The Cancer Genome Atlas (TCGA) consortium reported mutations in ELF3 in ~6% of both superficial and invasive tumours, over half of which were inactivating mutations." (PMID 30200227, 2018). "For instance, in bladder cancer cells, overexpression of ELF3 reduced invasion and expression of mesenchymal markers." (PMID 36864480, 2023). "Within bladder cancer patients, ELF3+ surrogate status is significantly predictive of lower survival (p-value 0.0281, n = 26)." (PMID 26779250, 2015). "Cluster M2 was enriched in LG bladder cancer, and M2 highly expressed transcription factors (ID1 and ELF3), thereby regulating epithelial cell development and mediating inflammatory signals." (PMID 35265520, 2022).
hepatocellular carcinoma (11 papers, 2012 to 2023). A malignant tumor that arises from hepatocytes. "Elf3, a member of the E-twenty-six family of transcription factors, has previously been implicated in the epithelial-mesenchymal transition in hepatocellular carcinoma cells." (PMID 36446858, 2022). "Other studies have shown that ELF3 overexpression is significantly associated with poor prognosis in patients with hepatocellular carcinoma (HCC)." (PMID 30498398, 2018). "In hepatocellular carcinoma, ELF3 promotes epithelial-mesenchymal transition by protecting ZEB1 from miR-141-3p-mediated silencing." (PMID 33070167, 2020). "ELF3 binds to the miR-141-3p promoter and it suppresses its expression, thereby promoting the epithelial-mesenchymal transition in human hepatocellular carcinoma." (PMID 31200542, 2019). "A previous research indicated that ELF3 promotes epithelial-mesenchymal transition (EMT) by regulating miR-141-3p leading to the enhancement of ZEB1, in hepatocellular carcinoma." (PMID 30429233, 2018).
lung adenocarcinoma (10 papers, 2019 to 2024). A carcinoma that arises from the lung and is characterized by the presence of malignant glandular epithelial cells. "ELF3 was also among the most upregulated genes in more advanced lung adenocarcinoma cells and correlated to heterogeneous tumor and immune cell populations." (PMID 39219440, 2024). "Besides, GEPIA database also indicated that ELF3 level was higher in lung adenocarcinoma tissues (n = 515) than in normal control tissues (n = 59)." (PMID 38169645, 2024). "This is consistent with the effect of high expression of ELF3 in human bronchial epithelial cells NL20 and human lung adenocarcinoma H1650 cells, i.e., ELF3 positively regulates cell growth." (PMID 39695109, 2024). "Because E74-like ETS transcription factor 3 (ELF3) was reported to bind to Notch-3 gene promoter with transcription regulation in K-RAS-mediated lung adenocarcinoma, we evaluated the interaction of KLF10 and ELF3 in Panc-1 cells." (PMID 37308977, 2023). "A549 lung adenocarcinoma cells treated with TGFβ to undergo EMT (GSE17708) showed a progressive decrease in ELF3 levels at later time-points of induction." (PMID 36864480, 2023). "An earlier report suggests that PKCλ activates NOTCH3 expression via ELF3 phosphorylation, and this axis maintains the highly tumorigenic TIC phenotype in KRAS-mediated lung adenocarcinoma." (PMID 32658903, 2020). "In UALCAN cancer database, the expression of ELF3 was significantly elevated in lung adenocarcinoma tissues (n = 483), compared to the noncancerous lung tissues (n = 347)." (PMID 38169645, 2024). "ELF3, playing an important oncogenic role in several tumors including PDAC, was reported to positively regulate Notch-3 gene transcription and modulate tumor-initiating cells in K-Ras-mediated lung adenocarcinoma." (PMID 37308977, 2023).
non-small cell lung carcinoma (9 papers, 2018 to 2025). A group of at least three distinct histological types of lung cancer, including non-small cell squamous cell carcinoma, adenocarcinoma, and large cell carcinoma. "ELF3 mRNA and protein expression is elevated in non-small cell lung cancer (NSCLC) compared to corresponding normal lung tissue, with high expression associated with poor patient outcome." (PMID 30200227, 2018). "Studies have found that ELF3 is differentially expressed in non-small cell lung cancer." (PMID 40429988, 2025). "Furthermore, the ELF3 locus is located within a region of recurrent DNA-level gain in non-small cell lung cancer on chromosome 1q32.1, suggesting a genetic mechanism of selection." (PMID 31780666, 2019).
ovarian carcinoma (9 papers, 2017 to 2025). A malignant neoplasm originating from the surface ovarian epithelium. "In the ovarian cancer epithelium samples we analyzed, we found that low ELF3 expression was associated with poor clinical outcome." (PMID 28199976, 2017). "To test our hypothesis, using immunohistochemistry and analysis of TCGA data, we validated the association between nuclear ELF3 expression and improved ovarian cancer patient survival." (PMID 28199976, 2017). "Furthermore, using 112 high-grade ovarian cancer samples isolated from patients and The Cancer Genome Atlas (TCGA) data, we found that downregulation of ELF3 expression was markedly associated with reduced survival." (PMID 28199976, 2017). "Like ETS transcription factor 3 (ELF3), E74 is a prognostic marker of ovarian cancer and can suppress the proliferation of ovarian cancer cells." (PMID 31973127, 2020). "Ovarian cancer cells with ELF3 overexpression exhibited a significant decrease in invasive potential (p < 0.001)." (PMID 28199976, 2017). "We observed significantly less tumor progression in the animals injected with ELF3-overexpressing ovarian cancer cells than in those injected with the control cells." (PMID 28199976, 2017). "Functional studies demonstrated that overexpression of ELF3 in ovarian cancer cells suppressed proliferation and anchorage-dependent growth of the cells and that ELF3 silencing increased cell proliferation." (PMID 28199976, 2017). "Through functional studies, we showed that ELF3 played a significant role in suppressing ovarian cancer progression as a negative regulator of epithelial-mesenchymal transition (EMT)." (PMID 28199976, 2017). "To determine the prognostic significance of ELF3 in ovarian cancer, we performed Cox regression and Kaplan-Meier survival analyses using ELF3 immunostaining data obtained from 112 advanced ovarian cancer patients." (PMID 28199976, 2017). "Soft agar assay results demonstrated that overexpression of ELF3 in the ovarian cancer cell lines OVCA429 and SKOV3ipluc decreased their ability to form colonies in soft agar." (PMID 28199976, 2017). "Based on our transcriptome analysis of ovarian cancer patients with long and short overall survival durations, we identified ELF3 as one of the most significantly upregulated transcription factors in long-term survivors." (PMID 28199976, 2017). "To validate the expression of the ELF3 in ovarian cancer cells, we performed immunolocalization of ELF3 in 22 serous borderline ovarian tumor (SBOT), 23 low-grade serous ovarian cancer (LGSC), and 127 high-grade serous ovarian carcinoma (HGSC) tissue samples." (PMID 28199976, 2017). "To demonstrate the inhibitory effects of ELF3 on ovarian tumor progression in vivo, we intraperitoneally injected female nude mice with SKOV3ipluc ovarian cancer cells stably transfected with an ELF3 expressing vector or a control vector." (PMID 28199976, 2017). "ELF3 was one of the genes whose expression was upregulated in microdissected ovarian cancer cells of long-term survivors." (PMID 28199976, 2017). "Immunohistochemical analysis of ELF3 in tumor tissue sections suggested that ELF3 was exclusively expressed by epithelial ovarian cancer cells." (PMID 28199976, 2017). "In contrast, expression of the mesenchymal elements N-cadherin, Slug, and vimentin decreased in ELF3-transfected ovarian cancer cells." (PMID 28199976, 2017). "With the small molecule-based and CRISPR/Cas9 library-based screening platforms avaliable, new therapeutic agents and signaling pathways that induce ELF3 expression, and subsequently improve ovarian cancer patient survival, can be identified." (PMID 28199976, 2017). "We further confirmed the prognostic significance of ELF3 expression by analyzing a TCGA Agilent microarray data with 385 ovarian cancer patients." (PMID 28199976, 2017). "As a negative regulator of EMT, ELF3-modulated reversal of EMT may be a new effective modality in the treatment of ovarian cancer." (PMID 28199976, 2017).